ZNF286B (zinc finger protein 286B (pseudogene))
Description:
May be involved in transcriptional regulation.
Synonyms: ZNF590; formerly ZNF286L; ZNF286C
Gene: Transcribed unprocessed pseudogene on chromosome 17 (18,661,937 to 18,681,846, reverse strand). Ensembl gene ENSG00000249459.
Subcellular location: Nucleus